HSPA2 (heat shock protein family A (Hsp70) member 2)
Diseases named in the same sentence as HSPA2 in open-access papers (continued):
Sharing a sentence is not in itself a finding about the gene and the disease.
lung adenocarcinoma (1 paper, 2022). A carcinoma that arises from the lung and is characterized by the presence of malignant glandular epithelial cells. "In a different study, it was noted that G1/S phase arrest occurred, and malignant cell proliferation decreased after the HSPA-2 gene was suppressed in lung adenocarcinomas." (PMID 35703525, 2022).
lung squamous cell cancer (1 paper, 2015). "On the other hand, HSPA2 expression can be detected at comparable levels both in tumor and corresponding normal tissue as exemplified by lung squamous cell cancer (SCC) tumors and normal bronchial epithelium." (PMID 25344376, 2015).
myocardial disease (1 paper, 2024). "This is particularly interesting as cardiotoxicity is known to arise from cancer therapies targeting ERBB3 (and related family members) and because other studies have implicated HSPA2 in other forms of myocardial disease." (PMID 39180332, 2024).
Obesity (1 paper, 2022). Accumulation of substantial excess body fat. "Subsequent research has shown that HSPA2 gene polymorphisms are highly correlated with obesity, where individuals with the homozygous genotype are susceptible to obesity, suggesting that HSPA2 may play a pivotal role in the initiation and progression of obesity and related metabolic disorders." (PMID 36636478, 2022).
osteoarthritis (1 paper, 2019). A noninflammatory degenerative joint disease occurring chiefly in older persons, characterized by degeneration of the articular cartilage, hypertrophy of bone at the margins and changes in the synovial membrane. "By validation of DEGs of GSE55457, three common proteins, PIM1, CYP1B1, and HSPA2, were considered as the key targeted proteins of the quercetin during the treatment of osteoarthritis by Achyranthes bidentata." (PMID 31998395, 2019). "After validation by GSE55457, PIM1, CY1B1, and HSPA2 were considered as the key proteins during the treatment of osteoarthritis by quercetin." (PMID 31998395, 2019). "In conclusion, the docking of PIM1-quercetin, CYP1B1-quercetin, and HSPA2-quercetin may play important roles during the treatment of osteoarthritis by Achyranthes bidentata." (PMID 31998395, 2019). "The docking of PIM1-quercetin, CYP1B1-quercetin, and HSPA2-quercetin may play important roles during the treatment of osteoarthritis by Achyranthes bidentata." (PMID 31998395, 2019).
ovarian carcinoma (1 paper, 2024). A malignant neoplasm originating from the surface ovarian epithelium. "Furthermore, FCGBP, MAP4K2, IL12A, and HSPA2 showed similar expression levels in ovarian cancer compared to normal tissues." (PMID 39149564, 2024).
sarcopenia (1 paper, 2021). Progressive decline in muscle mass due to aging which results in decreased functional capacity of muscles. "From the GEO profiles, the sarcopenia gene set variation analysis score was correlated significantly with the mRNA expression of APLNR (p < 0.001) and HSPA2 (p < 0.001)." (PMID 33743591, 2021).
systemic lupus erythematosus (1 paper, 2013). An autoimmune multi-organ disease typically associated with vasculopathy and autoantibody production. "Furthermore, polymorphism in the HSPA2 gene is associated with an increase in the risk of developing type 1 diabetes, non-Hodgkin's lymphoma, lung cancer, systemic lupus erythematosus (SLE), rheumatoid arthritis and inflammatory bowel diseases." (PMID 23777267, 2013).
tongue cancer (1 paper, 2015). A malignant neoplasm affecting the tongue. "After comparison between tongue cancer and corresponding normal samples, GNA15, PPP2R3A, LAMB3, HSPA2, and MAP4K3 were identified as five top-ranking genes." (PMID 26336805, 2015).
toxoplasmosis (1 paper, 2019). A parasitic disease contracted by the ingestion or fetal transmission of toxoplasma gondii.
viral infections (1 paper, 2023). "HSPA2 and HSPA1L do not show clear changes in other viral infections or HIV-1 infections, because they are enriched in testicular tissue, which may play vital roles in the process of HIV-1 invasion." (PMID 36845091, 2023).
cancer (37 papers, 2011 to 2025). A tumor composed of atypical neoplastic, often pleomorphic cells that invade other tissues. "In this study, for the first time, we directly compared the phenotypic effects of HSPA2 deficiency in cancer and corresponding normal cells." (PMID 32987811, 2020). "We have observed that patients with high expression of HSPA2 (better prognosis) were associated with smaller tumors (p = 0,0162), ER-positive and PR-positive cancers (p < 0,0001 and p < 0,0001, respectively)." (PMID 31101846, 2019). "Previously we found that in primary NSCLC, HSPA1 was associated with good prognosis while HSPA2 correlated with bad prognosis, suggesting possible different roles of these proteins in cancer." (PMID 31591429, 2019). "Although the underlying mechanism of HSPA2 in cancer metastasis was less documented, its critical role in tumor growth and metastatic potential had been assumed." (PMID 26930648, 2016). "Microarray analysis indicated that the enforced JAG1 transcription was associated with an elevated HSPA2 RNA transcription, which played a role in promoting cancer cell migration and invasion." (PMID 26930648, 2016). "The study of cancer cells pointed to the possible activation of the HSPA2 expression by hypoxia, a condition frequently associated with tumor propagation." (PMID 25344376, 2015). "Three different siRNAs or siRNA pools each for HSPA1A/HSPA1B and HSPA8 and, in addition, siRNA pools against HSPA2, which is expressed in a tissue specific manner and was implicated in cancer cell survival, and HSPA5 were utilized." (PMID 24265689, 2013). "The polymorphism of HSPA2 acts as an attractive susceptibility marker and independent prognostic indicator in Kangri cancer patients." (PMID 23777267, 2013). "Thus, uncertainty as to the value of HSPA2 as a cancer biomarker underlines the necessity to use validated and reliable tools for HSPA2 detection in tumor samples." (PMID 32987811, 2020). "Because each study cited above exploited a different cancer cell line and different gene silencing strategies, it is evident that more systematic studies are needed in order to understand the cause of the variable effects of HSPA2 deficit on growth of cancer cells." (PMID 25344376, 2015). "HSPA2 is expressed in somatic tissues and during mouse embryogenesis, and high levels of HSPA2 expression play a critical role in the genesis and progression of carcinoma." (PMID 40063400, 2025). "HSPA2 is a testis-enriched chaperone, which garnered attention as a significant protein in cancer with potential biomarker significance." (PMID 38791430, 2024). "A member of the HSP family, heat shock protein A2 (HSPA2), has recently emerged as an important cancer‐related protein with potential biomarker implications." (PMID 37306188, 2023). "HSPA2 is also ubiquitous in various types of cancer cells, but in vitro studies put under question its importance for cytoprotective or cancer-promoting mechanisms in lung, breast, or cervical cancer cells." (PMID 36959387, 2023). "Previously, we have found that proteotoxic stress provokes a decrease in HSPA2 levels in cancer cells." (PMID 36959387, 2023). "Previous studies have shown that HSPs are differentially expressed in different cancers, including HSPA2 and HSPA1A." (PMID 34712697, 2021). "In turn, HIF-1α upregulates the HSPA2/HSP70-2 expression in cancer cells that is important for their growth and survival." (PMID 33806538, 2021). "Taking into account that complex mechanisms can control the impact of HSPA2 on the fate of cancer cells, it seems particularly important to evaluate the reliability and usefulness of HSPA2 as a cancer biomarker." (PMID 32987811, 2020). "Several previous in vitro studies have shown significant role of HSPA2 in supporting cancer cells growth and invasiveness." (PMID 32987811, 2020). "We showed that only one from among six commercial anti-HSPA2 antibodies ensured specific detection of HSPA2 in cancer cells and tissues." (PMID 32560263, 2020).
cancer (continued). "The IHC technique was used in several studies aimed at evaluating HSPA2 as potential cancer biomarker." (PMID 32560263, 2020). "The specificity of antibodies was also examined in a model system comprising genetically engineered isogenic cell lines differing by HSPA2 expression status, as well as in cancer cells under proteotoxic stress conditions in vitro, and in primary lung tumors." (PMID 32560263, 2020). "In the presented study, we showed that a large part of the current belief on cancer-related HSPA2 features stems from research performed with the use of non-validated and/or non-specific antibodies." (PMID 32560263, 2020). "In this study, we rather aimed at evaluating the reliability of current data on the role of HSPA2 in the cancer process, indicating that some of the results obtained using anti-HSPA2 antibodies should be revised." (PMID 32560263, 2020). "Recently, HSPA2 has drawn wider attention as a possible cancer-related protein and potential cancer biomarker." (PMID 32560263, 2020). "Our findings addressed concerns on some published studies dealing with HSPA2 as a cancer-related protein." (PMID 32560263, 2020). "In relation to the cancer, it would be important to critically verify the alleged functional and clinical significance of HSPA2 in cancer cells using reliable, validated researched tools and experimental models." (PMID 32987811, 2020). "Nevertheless, conflicting conclusions have been recently drawn both according to HSPA2 role in cancer cells, as well as to its prognostic value." (PMID 32560263, 2020). "Although research on the involvement of HSPA2 in cancer is in early stage, results of several clinically oriented correlation studies revealed association between HSPA2 expression and patients survival." (PMID 32560263, 2020). "The essential role of HSPA2 in supporting viability, motility, adhesiveness, and invasiveness was also revealed in studies performed on different cancer cell lines after transient shRNA-mediated knockdown of HSPA2." (PMID 32987811, 2020). "One of them is HSPA2 which recently was indicated as a novel cancer-related protein due to its elevated expression in various tumors and reported prognostic significance." (PMID 32987811, 2020). "Taking together our previous observations that HSPA2 deficit neither affects the growth nor chemoresistance of two NSCLC cell lines, our studies put the current belief on the universal cancer-related role of HSPA2 under question." (PMID 32987811, 2020). "It is possible that under some circumstances, HSPA2, as a signaling molecule, is released from certain types of cancer cells in order to modulate tumor microenvironment or immunological response." (PMID 32987811, 2020). "HSPA1 is among the best characterized cancer-related chaperones, while the significance of HSPA2 for cancer remains poorly understood." (PMID 31591429, 2019). "HSPA2, whose abnormal expression is usually found in a subset of cancers, has also been identified as a potential tumor-promoting protein." (PMID 26879937, 2016). "The expression of the HSPA2 gene, both at protein and mRNA levels, was also demonstrated by several groups in cancer cell lines originated from various human malignancies as well as in primary malignant tumors." (PMID 25344376, 2015). "The aim of this review is to summarize the current knowledge on HSPA2 gene expression and regulation as well as to discuss possible functions of the gene in spermatogenic, normal somatic, and cancer cells." (PMID 25344376, 2015). "We discuss the possible influence of HSPA2 on cancer phenotype in the later section of this review (“Function of HSPA2 in normal somatic and cancer cells” section)." (PMID 25344376, 2015). "One of the most important issues is to determine to what extent HSPA2 influences survival and proliferation of cells of various cancer histotypes." (PMID 25344376, 2015).
cancer (continued). "We also present and discuss the current views concerning the functions of the HSPA2 protein in spermatogenetic, somatic, and cancer cells." (PMID 25344376, 2015). "As a chaperone protein, HSPA2 is essential for the growth of spermatocytes and cancer cells, and it is known to be involved in apoptosis and regulation of cell proliferation." (PMID 23777267, 2013). "Heat shock-related 70 kDa protein 2 (HSPA2) has been identified as a potential cancer-promoting protein expressed at abnormal levels in a subset of cancers." (PMID 23777267, 2013). "At physiological temperature, the HSPA2 is localized primarily in cytoplasm, whereas the HSPA2 localization shifts to the nucleus and nucleoli in heat-hock cancer cells." (PMID 23777267, 2013). "Our results demonstrate that PC-3 and HeLa cancer cells require tNASP to maintain high levels of HSPA2 activity and therefore viability, while PWR-1E cells are unaffected by tNASP depletion." (PMID 21496299, 2011). "HSPA2 is required for the survival of cancer cells; HSPA2 depletion has been reported to arrest cells in G1 and up regulate p21 expression." (PMID 21496299, 2011). "Furthermore, we found that HSPA 2 (Heat shock protein family A member 2), a prominent cancer chaperonic protein, was downregulated in bergenin-treated cells." (PMID 38961106, 2024). "In the present study we found that proteasome inhibition-related loss of HSPA2 from cancer cells neither is related to a block in the gene transcription nor does it relate to increased autophagy-mediated disposals of the protein." (PMID 36959387, 2023). "We have found that HSPA2 is indeed a component of EVs released from both cancer and normal cells." (PMID 36959387, 2023). "One explanation of this surprising phenomenon is that HSPA2 can be the subject of various post-translational modifications that may differentiate its function or intracellular trafficking in cancer cells." (PMID 32987811, 2020). "The earliest study in cancer cells showed that the small interfering RNA (siRNA)-mediated partial knockdown of HSPA2 significantly reduced growth and produced a distinct phenotype from that caused by the HSPA1A/B knockdown, thus pointing to a possible functional diversity between HSPA1 and HSPA2." (PMID 32987811, 2020). "An attractive and acceptable explanation of these discrepancies is that the dependence of cancer cells on HSPA2 activity may arise only on the specific molecular background." (PMID 32987811, 2020). "Interestingly, HIF-1 in relation to the HSPA2 gene seems to act as a transcriptional activator in cancer cells, but as a repressor in keratinocytes." (PMID 31734893, 2019). "Thus, it seems reasonable to assume that the degree of reliance on HSPA1 or HSPA2 for cell proliferation can differ in cancer cells of diverse histological origin and/or depending on cellular context." (PMID 31591429, 2019). "For HSPA2 we observed correlation with both good and bad prognosis depending on cancer types." (PMID 31101846, 2019). "However, a significance of HSPA2 for cancer diagnosis, prognosis, or treatment has to be determined." (PMID 31734893, 2019). "HSPA2 is involved in cancer cell survival in many tissues and is essential for spermatogenesis." (PMID 28265575, 2017). "This is widely different to findings of HSPA2 expression pattern in other cancer types." (PMID 26576432, 2015). "HSPA2 has been highlighted as an important biomarker in many cancer types." (PMID 26576432, 2015). "Moreover, downregulation of lens epithelium-derived growth factor (LEDGF) is responsible for the death of HSPA2-depleted cancer cells and LEDGF possesses great oncogenic potential." (PMID 23777267, 2013). "However, heat shock protein family members such as HSC70 and HSPA2 may play inhibitory roles in cancer cell invasion and metastasis." (PMID 35957827, 2022).
cancer (continued). "Thus, in certain cancers, the availability of specific NEFs and other co-chaperones, and/or their post-translational modifications might regulate the requirement for HSPA2 input into the HSPA chaperone machine." (PMID 32987811, 2020). "Thus, some published data on HSPA2 expression and function in human cancers should be considered with caution and may need to be reexamined." (PMID 32560263, 2020). "However, patients with low HSPA2 expression cancer had a shorter overall survival time." (PMID 26576432, 2015). "Finally, all of the observations above allow to propose that HSPA2 could play different roles in various types of cancer, depending on whether this protein was expressed in cancer precursors or its expression was acquired during oncogenic transformation." (PMID 25344376, 2015). "Therefore, depletion of tNASP should result in lesser amounts of HSPA2 activity implying that the interaction of tNASP and HSPA2 may be an important factor in the differential response of cancer cell lines to the depletion of tNASP." (PMID 21496299, 2011). "In the present study we have demonstrated that HSPA2, one of the most peculiar and least characterised members of the HSPA family, is released to extracellular space from both normal and cancer cells under physiological and stressful conditions." (PMID 36959387, 2023). "Next, we also explored HSPA2 and HSPA5 expression based on nodal metastasis status and individual cancer stage." (PMID 36982218, 2023). "Above all, HSPA2 and HSPA5 expression levels were found to be significantly downregulated or upregulated in cancer tissues compared with normal tissues." (PMID 36982218, 2023). "We selected these paralogs since they are regarded as important cancer-related chaperones; HSPA1 is believed to have potent cytoprotective roles, while contribution of HSPA2 to cytoprotection is debatable." (PMID 34200371, 2021). "The gene signature with strong invasive potential was enriched in 'Pathways in cancers' and 'MAPK pathway', with significantly higher in situ INSM1 and HSPA2 protein expression in invasive NF-PitNEts." (PMID 33391466, 2021). "Our results show that HSPA2 contributes to HBEC phenotype, but its deficit has a negligible impact on the viability, growth, migration, invasion, and adhesion of cancer cells." (PMID 32987811, 2020). "Altogether, these results indicate a functional redundancy between HSPA2 and other HSPA paralogs in various types of cancer cells." (PMID 32987811, 2020). "HSPA2 is one of the least characterized HSPA paralogs, and the current understanding of its role(s) in somatic and cancer cells remains very limited." (PMID 32987811, 2020). "Heat Shock Protein A2 (HSPA2), a testis-enriched chaperone and one of the least characterized members of the HSPA family, has recently emerged as an important cancer-relevant protein with potential biomarker significance." (PMID 32560263, 2020). "In cancer cells IC50 value of VER was the highest for NCI-H520 cells, which expressed HSPA1, HSPA2 and HSPA8 proteins at low levels in comparison to other NSCLC cell lines in our model." (PMID 31591429, 2019). "HSPA2 is a member of the HSP70 family of heat shock proteins and is important for cancer cell growth and metastasis." (PMID 26576432, 2015). "It has been shown that heat shock-related 70-kDa protein 2 (HSPA2), a member of the HSP70 family of heat shock proteins, is important for cancer cell growth and metastasis." (PMID 25890028, 2015). "HSPA2 and HSPA6 showed elevated gene expression in 9 and 10 out of 21 human cancers, respectively, which was predictive of a lower overall survival for one cancer for each chaperone." (PMID 35311075, 2022). "Conversely, using siRNA-mediated gene silencing, it was shown that neither HSPA2 nor HSPA1 were essential to cancer cells’ viability." (PMID 32987811, 2020). "HSPA2 also emerged as a cancer-related chaperone; however, no consensus on its functional significance has been reached so far." (PMID 32987811, 2020).